SPI1 (Spi-1 proto-oncogene)
Description:
Pioneer transcription factor, which controls hematopoietic cell fate by decompacting stem cell heterochromatin and allowing other transcription factors to enter otherwise inaccessible genomic sites. Once in open chromatin, can directly control gene expression by binding genetic regulatory elements and can also more broadly influence transcription by recruiting transcription factors, such as interferon regulatory factors (IRFs), to otherwise inaccessible genomic regions. Transcriptionally activates genes important for myeloid and lymphoid lineages, such as CSF1R (By similarity). Transcriptional activation from certain promoters, possibly containing low affinity binding sites, is achieved cooperatively with other transcription factors. FCER1A transactivation is achieved in cooperation with GATA1 (By similarity). May be particularly important for the pro- to pre-B cell transition. Binds (via the ETS domain) onto the purine-rich DNA core sequence 5'-GAGGAA-3', also known as the PU-box. In vitro can bind RNA and interfere with pre-mRNA splicing (By similarity).
Synonyms: PU.1; SPI-A; OF; SFPI1; SPI-1; AGM10
Tractability: Small molecule: a structure with a bound ligand is known. PROTAC: its protein half-life has been measured.
Gene: Protein-coding gene on chromosome 11 (47,354,860 to 47,409,369, reverse strand). Ensembl gene ENSG00000066336.
Subcellular location: Nucleus
Subcellular location (Human Protein Atlas): Nucleoplasm
Pathways (Reactome):
Developmental Biology: Transcriptional regulation of granulopoiesis
Gene expression (Transcription): RUNX1 regulates transcription of genes involved in differentiation of HSCs
Gene Ontology:
Molecular function: cis-regulatory region sequence-specific DNA binding; DNA-binding transcription activator activity; DNA-binding transcription factor activity; DNA-binding transcription factor binding; DNA-binding transcription repressor activity; protein binding; RNA polymerase II cis-regulatory region sequence-specific DNA binding; RNA polymerase II-specific DNA-binding transcription factor binding; sequence-specific DNA binding; STAT family protein binding; transcription cis-regulatory region binding; chromatin binding; DNA-binding transcription factor activity, RNA polymerase II-specific; histone deacetylase binding; NFAT protein binding; protein sequestering activity; DNA binding; DNA-binding transcription activator activity, RNA polymerase II-specific; DNA-binding transcription repressor activity, RNA polymerase II-specific
Biological process: defense response to tumor cell; interleukin-6-mediated signaling pathway; myeloid leukocyte differentiation; negative regulation of canonical NF-kappaB signal transduction; negative regulation of DNA-templated transcription; negative regulation of gene expression; negative regulation of non-canonical NF-kappaB signal transduction; negative regulation of transcription by RNA polymerase II; positive regulation of B cell differentiation; positive regulation of miRNA transcription; positive regulation of transcription by RNA polymerase II; regulation of DNA-templated transcription; regulation of erythrocyte differentiation; TRAIL-activated apoptotic signaling pathway; transcription initiation-coupled chromatin remodeling; cell differentiation; endothelial to hematopoietic transition; negative regulation of adipose tissue development; negative regulation of neutrophil degranulation; negative regulation of protein localization to chromatin; oncogene-induced cell senescence; pericyte cell differentiation; positive regulation of antifungal innate immune response; positive regulation of microglial cell mediated cytotoxicity; positive regulation of p38MAPK cascade; and 15 more
Cellular component: chromatin; nucleoplasm; nucleus; transcription regulator complex
Genetic constraint (gnomAD): Loss-of-function variants: 3 observed, 25.88 expected, observed/expected ratio (o/e) 0.12, 90% interval 0.052 to 0.3. The upper end of that interval is the gene's LOEUF score, 0.3, which puts it in group 1 of 6, group 1 being the genes least tolerant of losing a copy. Missense variants: 261 observed, 344.77 expected, observed/expected ratio (o/e) 0.76, 90% interval 0.68 to 0.84. Synonymous variants: 169 observed, 144.5 expected, observed/expected ratio (o/e) 1.17, 90% interval 1.03 to 1.33.
Gene-disease validity (ClinGen):
ClinGen rates the evidence that SPI1 causes each of these diseases.
agammaglobulinemia 10, autosomal dominant (autosomal dominant): Definitive. An agammaglobulinemia characterized by early-childhood onset of recurrent viral and bacterial infections affecting various organ systems, particularly the sinopulmonary system.
Homologues: Orthologues: chimpanzee SPI1 (100% identical), macaque SPI1 (99% identical), dog SPI1 (97% identical), pig SPI1 (93% identical), rat Spi1 (89% identical), mouse Spi1 (89% identical), guinea pig SPI1 (80% identical), tropical clawed frog spi1 (68% identical), zebrafish spi1b (57% identical). Paralogues in human: SPIB (42% identical), SPIC (29% identical), ETS2 (23% identical), ETS1 (21% identical), ETV5 (21% identical), ETV6 (20% identical), ETV1 (20% identical), ELF1 (19% identical), ETV4 (19% identical), ETV7 (19% identical), GABPA (19% identical), ERG (18% identical), and 16 more.
Diseases named in the same sentence as SPI1 in open-access papers:
SPI1 is named in the same sentence as 272 diseases in open-access papers, as found by Europe PMC text mining. Sharing a sentence is not in itself a finding about the gene and the disease. The quoted sentences say what the papers report.
leukemia (92 papers, 2008 to 2026). A malignant (clonal) hematologic disorder, involving hematopoietic stem cells and characterized by the presence of primitive or atypical myeloid or lymphoid cells in the bone marrow and the blood. "Deregulation of its activity or expression is associated with leukemia, in which SpI1 can act as either an oncogene or a tumor suppressor." (PMID 33869191, 2021). "In mouse, erythroleukaemias are associated with Friend virus infection where a clonal leukaemia develops through the proviral insertional activation of Spi1/Pu.1 leading to overexpression of PU.1." (PMID 27250028, 2016). "Additionally, FANCA loss of function in leukaemic SPI1-overexpressing cells deregulates a complex network of genes known for their strong association with leukaemia development." (PMID 37573408, 2023). "In addition to mice mutated in Pax5 or Ikzf1, Irf4/Irf8−/−, and Irf4/Spi1−/− mice have been shown to develop leukemia early in life at a high incidence." (PMID 35459909, 2022). "The results showed that SPI1 mRNA expression was upregulated significantly in GC and certain other tumors, whereas it was downregulated in colon cancer, lung cancer, and leukemia; this difference may have been caused by the different potential pathogenic mechanisms involved in these cancers." (PMID 35237521, 2022). "Deregulated expression of multiple ETS factors like ERG, FLI1 and SPI1 contribute to the genesis of leukemia and impact the survival outcome in leukemia patients." (PMID 37895265, 2023). "In tumors, SPI1 was initially studied more frequently in leukemia, but SPI1 was later reported to play a promoting role in other cancers 59-61." (PMID 37351164, 2023). "SMARCA5, through the interaction with CTCF in leukemic cells, actively inhibits expression of the SPI1/PU.1 gene that represents key hematopoietic transcription factor and dose-dependent leukemia suppressor." (PMID 32197313, 2020). "Initial studies also indicate that SPI1 is a putative oncogene and has a key relationship with leukemias." (PMID 30935420, 2019). "Both SPI1 sites overlap with regions of DNase I hypersensitivity, suggesting these promoter regions are bound by regulatory proteins in lymphocytes and leukemia cells." (PMID 27506447, 2016). "In normally differentiating myeloid cells both CTCF and SMARCA5 together with members of the Cohesin complex are recruited to the SPI1 gene, a key hematopoiesis regulator and leukemia suppressor." (PMID 24498324, 2014). "Additional assays are required to examine whether SPI1 is related to elevated PIK3R5 in this leukemia subset." (PMID 39507412, 2024). "Thus, transgenic Spi1-overexpressing (TgSpi1) mice represent a preleukaemic state towards the development of leukaemia." (PMID 37573408, 2023). "In addition, inferior overall survival is also observed in AML leukemia patients with high SPI1 expression." (PMID 37895265, 2023). "Compared with that in normal tissues, SPI1 expression was higher in brain cancer, head and neck cancer, breast cancer, GC, kidney cancer, pancreatic cancer, and lymphoma; and lower in colorectal cancer, lung cancer, and leukemia." (PMID 35237521, 2022). "Furthermore, SPI1/PU.1 has been instigated in leukemia, Alzheimer's disease and, notably in the context of epileptogenic pathologies, in the chronic transcriptional changes that result from experimental traumatic brain injury (TBI) in rats." (PMID 33786950, 2021). "Although the PTEN loss and Tcra/d-Myc translocation in the first layer of the leukemogenesis mechanism are hardwired and present in both LSCs and leukemia blasts, the SPI1 expression and maintenance in the second layer of the LSC ‘stemness’ mechanism is reversible and present only in LSCs." (PMID 30412053, 2018). "The presence of SPI1 at GLR enhancers may provide an explanation for the observation that murine leukemias with reduced PU.1 levels are relatively resistant to the consequences of LSD1 inhibition." (PMID 29590629, 2018).
leukemia (continued). "In leukemia, METTL14, which is negatively regulated by SPI1, exerts its oncogenic effects by regulating m6A modification of its mRNA targets (e.g., MYB and MYC)." (PMID 37932821, 2023). "Our data together suggest that RNA and hnRNPK mediate 5-AZA-sensitive interactions between the lineage-determining factors (GATA1 and SPI1/PU.1) and chromatin modifiers in the OCI-M2 and SC leukaemia cells." (PMID 29563491, 2018). "In SPI1-METTL14-MYB/MYC axis, METTL14, is downregulated by SPI1, exerts an oncogenic role in enhancing leukemia stem/initiating cells self-renewal and repressing myeloid differentiation by regulating MYB and MYC via m6A modification." (PMID 30062093, 2018). "For example, SPI1/PU.1 contributes to erythropoiesis and hematopoiesis, and CEBPB suppresses leukemia pathogenesis through the inhibition of proliferation." (PMID 27783037, 2016). "Cross‐talk between SPI1 and the MEIS/HOX gene regulation pathway has been noted in mixed lineage leukemia." (PMID 27506447, 2016). "Importantly for genetic counseling, despite the link between somatic SPI1 mutations and leukemia, no significant increase in hematologic malignancies was observed in the large cohort of germline variant carriers, suggesting that PU.1 haploinsufficiency may not confer a strong leukemic risk." (PMID 41394874, 2025). "In keeping with this, CIMP leukemias also exhibited increased methylation at NOTCH1, MYB, and TAL1 binding sites than ETP-ALL, and hypomethylation of TFBS for myeloid master regulators such as CEBPA, CEBPB, and SPI1." (PMID 38972954, 2024). "While sufficient evidence confirms the regulation of PIK3R5 by SPI1, it is still unclear whether the observed SPI1-PIK3R5 axis occurs in the leukemia subset defined by elevated PIK3R5." (PMID 39507412, 2024). "Moreover, binding sites for hematopoietic transcription factors, including CEBPA, SPI1 and LEF1, are uniquely inaccessible in these leukemias." (PMID 38972954, 2024). "Joint expression of SPI1 and IHH results in the appearance of self-renewing leukemic cancer stem cells erythroid progenitors are infected with viruses with subsequent occurrence of leukemia." (PMID 28031533, 2017). "Also, an antagonistic role for SPI1 and HOXC13 in erythroid cell differentiation has been proposed based on data from erythro leukemia cell lines." (PMID 27506447, 2016).
acute myeloid leukemia (61 papers, 2009 to 2026). Acute myeloid leukemia (AML) is a group of neoplasms arising from precursor cells committed to the myeloid cell-line differentiation. "Master regulators of hematopoietic lineages have been implicated in tumor suppressor function, as reported for C/EBPα and SPI1/PU.1 in acute myeloblastic leukemia (AML) or PAX5 loss of function in B-ALL." (PMID 35401501, 2022). "PU.1 (or SPI-1, of the SPI subfamily) plays an essential role in lineage commitment of haematopoietic precursor cells into macrophages and monocytes whereby impaired PU.1 function has been linked to the development of acute myeloid leukaemia (AML)." (PMID 34066106, 2021). "Mice carrying hypomorphic SPI1 alleles that reduce PU.1 expression to 20% of its normal levels exhibit blockade of myeloid differentiation, leading to the development of acute myeloid leukemia (AML)." (PMID 25072246, 2014). "However, acute myeloid leukemia can result from loss‐of‐function mutations in SPI1 or reduced Spi1 expression, while induced expression of SPI1 in myeloid leukemia cells restores their differentiation and reduces their proliferation rates." (PMID 27506447, 2016). "METTL14 was found to be negatively regulated by the SPI1 transcription factor both in normal and pathological conditions such as acute myeloid leukemia." (PMID 40940799, 2025). "Regarding theinteraction between SPI1 and KRAS, previous studies have verified their interactionin myeloid leukemia and radiotherapy-associated acute myeloid leukemia." (PMID 41259792, 2025). "In acute myeloid leukemia, inhibition of SPI1 using these inhibitors resulted in the downregulation of SPI1 downstream targets and reduced tumor burden." (PMID 36698141, 2023). "In addition, the decreased expression of SPI1 caused by heterozygous deletion of the SPI1 locus eventually leads to the occurrence of acute myeloid leukemia (AML)." (PMID 35237521, 2022). "Transcription factor SOX4 reduces mRNA levels of transcription factor PU.1 (SPI 1) in human acute myeloid leukemias." (PMID 25329802, 2014). "In addition, the regulating or inhibiting factors of m6A modifications may act as potential strategies for cancer treatments, as observed for MA2 in glioblastoma multiforme, R-2HG/SPI1/FB23-2 in acute myeloid leukemia, and CA4 in colorectal cancer." (PMID 33791305, 2021). "PU.1 (encoded by SPI1) is essential for myeloid development, and inhibition of its expression and activity can lead to acute myeloid leukemia (AML)." (PMID 33741901, 2021). "It has been reported that the expression of Mettl14 is negatively regulated by SPI1 in acute myeloid leukemia (AML) cells." (PMID 32444598, 2020). "SPI1 is an ETS family of transcription factors that play a crucial role in hematopoietic development and differentiation, and modulation of SPI1 expression has been implicated in the tumourigenesis of acute myeloid leukemia (AML)." (PMID 39697230, 2024). "Because homozygous Spi1-knockdown mice also become moribund from T-cell lymphoma and acute myeloid leukemia starting at 3 months of age10, we utilized only Spi1 heterozygous knockdown (Spi1+/−;APP/PS1) mice and wild-type for Spi1 (Spi1+/+;APP/PS1) mice." (PMID 38734693, 2024). "It was reported that METTL14 overexpression in acute myeloid leukemia is negatively regulated by SPI1 and mediates downstream targets, MYB and MYC, to accelerate acute myeloid leukemia (AML) oncogenesis." (PMID 34904301, 2022). "The N-terminal SNAG domain of the transcriptional repressor GFI1 binds to the CoREST transcriptional complex proteins LSD1 and RCOR1 at the enhancers of transcription factor genes, such as SPI1 (PU.1), CEBPA and IRF8 which are important for acute myeloid leukemia cell differentiation." (PMID 38135679, 2023). "In addition, METTL3 depletion in HSCs did not affect apoptosis, whereas knocking down of METTL14 induced acute myeloid leukemia (AML) cell apoptosis and promoted myeloid differentiation of normal HSCs via the SPI1–METTL14–MYB/MYC signaling axis." (PMID 35935968, 2022).
acute myeloid leukemia (continued). "For the first time, Weng and coworkers described the signaling axis SPI1-METTL14-MYB/MYC in normal myelopoiesis and leukemogenesis and proposed that METTL14 could be a new therapeutic target to treat acute myeloid leukemia (AML)." (PMID 40940799, 2025). "In our previous studies with mice lacking a key Spi1 (encoding PU.1) cis-enhancer termed upstream regulatory element (URE), we found that UREΔ animals, which harbor downregulated PU.1 expression, eventually succumb to lethal acute myeloid leukemia (AML)." (PMID 39543396, 2024).